CD86 (CD86 molecule)
Diseases named in the same sentence as CD86 in open-access papers (continued):
Sharing a sentence is not in itself a finding about the gene and the disease.
Immunodeficiency (3 papers, 2016 to 2024). Failure of the immune system to protect the body adequately from infection, due to the absence or insufficiency of some component process or substance. "Costimulatory proteins Cd274 (PD-L1), Ctla4 and Cd86 linked to the immune deficiencies observed in sepsis were upregulated across tissues (12/13 tissues for Cd274, 6/13 tissues for Cd86 and 3/13 tissues for Ctla4)." (PMID 38191855, 2024). "Naive B cells from patients with common variable immunodeficiency are markedly impaired in upregulating the costimulatory molecules CD86 and CD70 upon BCR cross-linking and the expression remained reduced even in the presence of autologous helper CD4+ T cells." (PMID 28116319, 2016).
injury (3 papers, 2011 to 2023). Damage inflicted on the body as the direct or indirect result of an external force, with or without disruption of structural continuity. "In a bleomycin-induced acute lung injury model we reported that hAECs can mediate macrophage polarization away from the pro-inflammatory M1 phenotype (CD86+) to the pro-reparative M2 phenotype (CD206+)." (PMID 28241859, 2017). "Flow cytometry analysis also showed that CP-7 induced a significant decline in the number of CD86-positive microglia, indicating that CP-07 could modulate the proinflammatory microglial phenotype switch following experimental I/R brain injury." (PMID 37408577, 2023).
juvenile idiopathic arthritis (3 papers, 2018 to 2024). Juvenile idiopathic arthritis (JIA) is the term used to describe a group of inflammatory articular disorders of unknown cause that begin before the age of 16 and last over 6 weeks. "To date, CTLA4 Ig (abatacept), which binds to CD80/CD86 and inhibits inflammatory T cell activation, has been approved by the US Food and Drug Administration to treat RA, juvenile idiopathic arthritis, and active psoriatic arthritis." (PMID 36271469, 2022).
latent infection (3 papers, 2017 to 2024). "KSHV downregulates MHC-I expression during lytic infection, and expression of ICAM-1 and B7-2 (CD86) during latent infection, allowing evasion of T cell and natural killer immunity respectively." (PMID 28881567, 2017). "Furthermore, an intercellular adhesion molecule-1 (ICAM-1) and B7-2 (CD86) were downregulated in the KSHV latent infection state, enabling T cell and NK cell immune evasion, respectively." (PMID 38966176, 2024). "CD80 and CD86 interact on APC and CD28 on T cells as costimulatory signals for the activation of T cells, are key players in anti-viral humoral and cellular immune responses, and play a critical role in the control of chronic and latent infections." (PMID 38674902, 2024).
Listeria infection (3 papers, 2019 to 2022). "The results showed that Listeria infection increased the expression of CD86 (M1 marker) in microglia." (PMID 31133815, 2019). "In contrast, monocytes from the listeria infection model expressed M1-related transcription factors (e.g., Irf2, Mndal, Ifi204) and showed higher expression of CD38, CD74, and CD86, as well as higher ROS production." (PMID 36010615, 2022). "The decreased expression of CD86, I-Ab, CD80, and CD40 was also observed in Mettl3KO splenic DC after Listeria monocytogens infection." (PMID 31015515, 2019).
Miscarriage (3 papers, 2014 to 2021). A pregnancy that ends at a stage in which the fetus is incapable of surviving on its own, defined as the spontaneous loss of a fetus before the 22th week of pregnancy. "Our previous animal investigation showed the positive role of CsA in improving the biological functions trophoblast cells and inducing maternal-foetal tolerance in miscarriage-prone mice with a high mRNA level of CD80/CD86." (PMID 33726772, 2021).
myocardial infarction (3 papers, 2024 to 2025). Gross necrosis of the myocardium, as a result of interruption of the blood supply to the area, as in coronary thrombosis. "The OHA-PL@Exo hydrogel demonstrated the ability to eliminate reactive oxygen species, reduce the expression of the M1 macrophage-related protein CD86, and diminish inflammation during the initial stage of myocardial infarction (MI)." (PMID 40001724, 2025). "Following myocardial infarction (MI), the accumulation of CD86-positive macrophages in the ischemic injury zone leads to secondary myocardial damage." (PMID 39752485, 2025).
nasal polyp (3 papers, 2013 to 2025). "In the nasal polyp tissues, DCs induce an imbalance in the proportion of the Th1/Th2 cells by causing the expression of CD80/CD86 to become unbalanced." (PMID 23737902, 2013). "Elevated numbers of CD86+ cells were found in nasal polyps, leading to enhanced Th2 inflammation." (PMID 36466903, 2022).
nasopharyngeal carcinoma (3 papers, 2007 to 2022). A carcinoma arising from the nasopharyngeal epithelium. "Herein, CD86 was immunohistochemically detected in 36 of the 255 patients (14.1%), which is similar to nasopharyngeal carcinoma patients (20.0%) and lower in non-small cell lung cancer (NSCLC) patients (53%)." (PMID 36428666, 2022). "A high-level expression of CD80 and CD86 may result in a high survival benefit of patients with nasopharyngeal carcinoma." (PMID 33092083, 2020). "This study examined the expression of B7-1 (CD80) and B7-2 (CD86) costimulatory molecules along with HLA-DR and the presence of infiltrating lymphocytes and dendritic cells to assess their significance in patients with nasopharyngeal carcinoma (NPC)." (PMID 17524139, 2007).
pituitary tumor (3 papers, 2021 to 2023). A benign or malignant neoplasm affecting the pituitary gland. "The increased expression of immune checkpoints, such as the programmed death ligand-1 (PD-L1) and the cytotoxic T-lymphocyte-associated protein 4 (CTLA-4) ligands CD80 and CD86, has been associated with aggressiveness in proliferative pituitary tumors." (PMID 37958702, 2023). "We found higher expression of PD-L2, CD80, and CD86 in aggressive pituitary adenomas when compared to normal pituitary tissues, suggesting the accumulation of peripheral immune cells like regulatory T cells, NK cells and dendritic cells in the pituitary tumor immune microenvironment (TIME)." (PMID 34745002, 2021). "Furthermore, aggressive pituitary tumors demonstrated significantly higher levels of CD80 and CD86 compared to non-aggressive tumors." (PMID 34745002, 2021).
preeclampsia (3 papers, 2020 to 2022). Preeclampsia is a hypertensive disorder of pregnancy that is characterized by new-onset hypertension with proteinuria presenting after 20 weeks of gestation, and depending on mild or severe forms may initially present with severe headache, visual disturbances, and hyperreflexia. "Another that DCs derived from the peripheral blood of preeclampsia patients expressed increased levels of CD80 and CD86." (PMID 36303229, 2022). "In other pregnancy complications, such as preeclampsia, peripheral DCs from patients express higher levels of both CD80 and CD86." (PMID 32265918, 2020). "M2 macrophages (CD136+MRC1+C1QA+C1QB+, P=0.007) and mast cells (TPSAB1, P=0.007) were decreased in early-onset preeclampsia samples, while M1 macrophages (CD86+MSR1+) were not altered based on gene expression." (PMID 34992598, 2021).
rectal adenocarcinoma (3 papers, 2019 to 2023). "TCM from 2Gy irradiated rectal adenocarcinoma significantly inhibited LPS-induced DC maturation, compared to 0Gy patient-matched biopsies for CD54 (p = 0.003), HLA-DR (p = 0.007), CD86 (p = 0.050) and PD-L1 (p = 0.036)." (PMID 32552799, 2020). "Moreover, the TCM from rectal adenocarcinoma significantly enhanced CD80 (p = 0.028), CD86 (p = 0.016) and CD83 (p = 0.002) compared to LPS-induction in background media alone, cRPMI (+)." (PMID 32552799, 2020). "However, we found a higher level of PD-L1, PD-L2, CD80, CD86, Tim-3, LAG3, and 4-1BB in EBV-positive STAD and cytomegalovirus-positive colon and rectum adenocarcinoma than in virus-negative tumor samples." (PMID 30911684, 2019).
Salmonella Infections (3 papers, 2015 to 2025). Infections with bacteria of the genus SALMONELLA. "In mouse peritoneal MΦs, Salmonella infection up-regulated the expression of both of M1 MΦ markers (CCR7 and CD86), M2 MΦ marker (CD163 and CD206) and induced the secretion of M1 MΦ marker TNF-α and M2 MΦ marker IL-10 in ascitic fluid significantly." (PMID 30271755, 2018). "Thus, the observed differences in survival of the mouse strains to oral Salmonella infection are independent of differential recruitment of myeloid cells, DC abundance, and expression of CD80 and CD86 on DCs in infected tissues." (PMID 26441965, 2015).
visceral leishmaniasis (3 papers, 2017 to 2025). A severe form of leishmaniasis characterized by irregular bouts of fever, substantial weight loss, swelling of the spleen and liver, and anemia (which may be serious). "On the contrary, in visceral leishmaniasis, the N-DC hybrids present at disease presentation expressed MHC class II, CD80, and CD86 but were associated with an anergic phenotype." (PMID 40340446, 2025). "A decreased T lymphocyte activation, possibly caused by a decrease in CD86 and an increase in CD80 expression, is consistent with the findings observed in human visceral leishmaniasis." (PMID 29358935, 2017).
acne (2 papers, 2021 to 2022). An inflammatory process of the sebaceous glands which is characterized by comedones, nodules, papules and/or pustules on the skin. "It is worth noting that both NLRP3 active caspase-1 are expressed by tissue macrophages CD86+ in acne lesions, which also suggests the participation of inflammasome complexes in acne pathogenesis." (PMID 35329904, 2022). "The hypothesis of an immune response burden in uninvolved skin in patients with acne is reinforced by the fact that we observed a high percentage of activated mast cells and macrophages (according to CD86 and CD40 expression) in UI biopsies." (PMID 34650562, 2021).
airway hyperresponsiveness (2 papers, 2014 to 2022). "In vivo, intratracheal administration of CD86 siRNA during OVA challenge reduced the production of IL-5, IL-13, and TARC release and ameliorated airway eosinophilia, airway hyperresponsiveness, and elevation of OVA-specific IgE." (PMID 25344652, 2014). "CD86 siRNA treatment ameliorated OVA-induced airway eosinophilia, airway hyperresponsiveness, and the elevations of OVA-specific IgE in the sera and IL-5, IL-13, and CCL17 in the bronchoalveolar lavage fluid, but not the goblet cell hyperplasia." (PMID 25344652, 2014).
allergic pneumonitis (2 papers, 2021 to 2023). "In this study, the macrophage CD markers revealed the predominance of CD206 immunopositive M2 phenotype in the allergic pneumonitis-only group and switched to CD86 positive M1 phenotype after CYP exposure." (PMID 37048067, 2023). "Comparing the immunoexpression of the two macrophage markers in each group revealed substantial expression of the M1 macrophage marker (CD86) in the CYP alone-exposed animals and predominant CD206 expression in the allergic pneumonitis group." (PMID 37048067, 2023).
anaplastic thyroid cancer (2 papers, 2018 to 2022). "Here, the expression of PD-L1, PD-L2, CD80, and CD86 was evaluated at the mRNA level in 94 patients affected by papillary thyroid carcinoma (PTC) and 11 patients affected by anaplastic thyroid carcinoma (ATC)." (PMID 30123257, 2018).
aneurysm (2 papers, 2022 to 2023). Bulging or ballooning in an area of an artery secondary to arterial wall weakening. "Simultaneously, the results also revealed an increase in CD86+ (a marker of M1 macrophages) cells in unruptured aneurysms compared with normal arteries (48.0% vs. 11.1%, P<0.0001) and a further increase in ruptured aneurysms (78.8% vs. 48.0%, P<0.0001)." (PMID 37223093, 2023). "Flow cytometry revealed anti‐inflammatory M2 (CD45+CD11b+CD163+) macrophages in BBAs are significantly enriched in numbers compared with both M1 (CD45+CD11b+CD86+) and M2 (CD45+CD11b+CD163+) macrophages in saccular aneurysms." (PMID 34970805, 2022).
Anxiety (2 papers, 2025). Intense feelings of nervousness, tension, or panic often arise in response to interpersonal stresses. "Our findings revealed significant upregulation of chemokines Ccl3, Ccl4, Ccl5 and the inflammatory mediator Cd86 in Asm KO-induced anxiety." (PMID 39905541, 2025). "The results show a significant correlation between anxiety behavioral indicators and CORT levels, inflammatory factors (IL-6, IL-1β, CD86, TNF-α, TGF-β, IL-10), 5-HT, and GABA." (PMID 40078708, 2025).
arthrosis (2 papers, 2022 to 2023). "In addition, a greater number of CD206+ cells and less CD86+ cells were observed in the arthrosis of CIA mice treated with PD-L1 analogs, especially DBCO/DSPE-PD-L1, indicating that dual-anchored PD-L1 possessed the ability of inhibiting M1 polarization of synovial macrophages." (PMID 37907476, 2023).
Ascites (2 papers, 2017 to 2018). Accumulation of fluid in the peritoneal cavity (between the layers of the peritoneum that lines the abdomen). "We conclude that levels of IL-10 found in OC-associated ascites positively correlate with the inhibitory properties of ascites on the TLR-mediated up-regulation of the co-stimulatory molecule CD86, as well as the production of the cytokines IL-6 and IL-12p40 but not TNFα." (PMID 28410380, 2017). "Ascites reduced the expression of the co-stimulatory molecule CD86 and decreased the T cell stimulatory capacity." (PMID 30687337, 2018). "In order to confirm the presence of one or more additional immunosuppressive factors, we neutralized IL-10 in DC cultures activated with R848 in the presence and absence of ascites and compared the levels of CD86 up-regulation and cytokine induction between these two treatment conditions." (PMID 28410380, 2017).
astrocytoma (2 papers, 2020 to 2021). "Significantly higher expression of CD86 was observed in Grade-III astrocytoma as compared with oligoastrocytoma and oligodendroglioma of the same grade, while oligodendroglioma presented lower CD86 expression as opposed to oligoastrocytoma (P<1.4*10-14)." (PMID 33954112, 2021).
atopic dermatitis (2 papers, 2015 to 2024). "However increased CD80 and CD86 are observed in chronically inflamed skin conditions, such as atopic dermatitis." (PMID 25992642, 2015).
brain injury (2 papers, 2020 to 2021). Acute and chronic (see also brain INJURIES, CHRONIC) injuries to the brain, including the cerebral hemispheres, CEREBELLUM, and brain STEM. "Another study showed that, after injury, CD86-positive cells were increased, and the relative proportion of CD206-positive cells was decreased, indicating that HI brain injury might promote M1 polarization and reduce M2 activation." (PMID 32403417, 2020).
celiac disease (2 papers, 2019 to 2022). An autoimmune genetic disorder with an unknown pattern of inheritance that primarily affects the digestive tract. "Different from celiac disease, ATI elicit a modest immune response in the gut, with a mild increase in CD68+ macrophages and a modest increase of lamina propria dendritic cells/macrophages expressing CD86 and MHC class II, as also confirmed in the present report." (PMID 31767938, 2019).
cerebral infarction (2 papers, 2024 to 2025). An ischemic condition of the brain, producing a persistent focal neurological deficit in the area of distribution of the cerebral arteries. "We further analyzed the expression differences of Pip5k1c, Nlgn2, Fzd2, Cd86, Agpat1, and Degs2 between the cerebral infarction at 3, 6, and 12 h and the control group." (PMID 40520774, 2025). "The AUC values of Pip5k1c, Nlgn2, Fzd2, Cd86, Agpat1, and Degs2 were all 1, suggesting that Pip5k1c, Nlgn2, Fzd2, Cd86, Agpat1, and Degs2 have good sensitivity and specificity for the diagnosis of cerebral infarction." (PMID 40520774, 2025). "M1 microglia (with TNF-α or CD86 as markers) generate pro-inflammatory factors, such as TNF-α, IL-1β, IL-6, and interferon-γ, which promote inflammation and exacerbate I/R injury and cerebral infarction." (PMID 39391701, 2024).
cerebral malaria (2 papers, 2021 to 2024). A sequestration of Plasmodium falciparum in the brain, which can cause coma and/or seizures. "In studies of mice with cerebral malaria, EPO treatment significantly inhibited DCs differentiation and reduced expression of costimulatory markers CD80 and CD86, and TLRs." (PMID 33796104, 2021).
chronic asthma (2 papers, 2014). An asthma that is characterized by the development of persistent airway inflammation and recurrent attacks of breathlessness and wheezing, which vary in severity and frequency. "However, in an animal model of acute exacerbation M2 macrophages triggered Th2 cytokines in CD4+ T-lymphocytes through the interaction with CD80/CD86, which was not seen in a model of mild chronic asthma." (PMID 24612750, 2014).
Chronic colitis (2 papers, 2013 to 2025). A chronic inflammatory disease of the large intestine (colon, cecum and rectum). "In mice, neutrophils isolated from chronic colitis lesions have been shown to express MHC II and CD86 and exhibit an APC capacity to present peptide antigen to CD4 T cells." (PMID 24278484, 2013).
Cirrhosis (2 papers, 2013 to 2023). A chronic disorder of the liver in which liver tissue becomes scarred and is partially replaced by regenerative nodules and fibrotic tissue resulting in loss of liver function. "Whether the activation phenotype is stable during HCV infection remains to be tested and in the future we will study a cohort of patients longitudinally and specifically look at memory B cell CD86 expression to see if increased expression predicts the development of fibrosis/cirrhosis." (PMID 23840845, 2013). "Monocytic cells from patients with cirrhosis showed reduced basal expression of CD86 and impaired ability to mount PAMP-induced CD86 compared with healthy controls at all stages of disease." (PMID 37928515, 2023).
cryoglobulinemia (2 papers, 2013 to 2015). Cryoglobulinemia is a type of vasculitis that is caused by abnormal proteins (antibodies) in the blood called 'cryoglobulins.' At cold temperatures, these proteins become solid or gel-like, which can block blood vessels and cause a variety of health problems. "We also identified markers of memory B cell activation that were specific for HCV patients with cryoglobulinemia (CD86, CD71, HLA-DR) and advanced liver disease (CD86)." (PMID 23840845, 2013). "Since only CD86 was associated with a history of symptoms, monitoring the expression of HLA-DR and CD71 could now be used to detect cryoglobulinemia prior to the onset of clinical disease." (PMID 23840845, 2013). "In addition, we have demonstrated that certain memory B cell activation markers (CD86, CD71 and HLA-DR) correlate with the development of HCV-associated cryoglobulinemia with CD71 and HLA-DR levels increasing independently of the presence of clinical symptoms." (PMID 23840845, 2013).
endometrial cancer (2 papers, 2023). Primary or metastatic malignant neoplasm involving the endometrium (mucous membrane that lines the endometrial cavity). "In the absence of comprehensive single cell omics data, we calculated the partial correlations between CD70 and CD86 genes with diverse immune cell type fractions based on CIBERSORT analysis of RNA expression profiles of tumors from endometrial cancer patients." (PMID 37106127, 2023).
endotoxemia (2 papers, 2019 to 2020). "In children with higher endotoxemia at the time of venepuncture, monocytes had significantly lower expression of CD86, which is a costimulatory molecule required for T-cell priming." (PMID 30985520, 2019).